IGLV5-48 (immunoglobulin lambda variable 5-48 (non-functional))
Description:
Probable non-functional open reading frame (ORF) of V region of the variable domain of immunoglobulin light chains. Non-functional ORF generally cannot participate in the synthesis of a productive immunoglobulin chain due to altered V- (D)-J or switch recombination and/or splicing site (at mRNA level) and/or conserved amino acid change (protein level). Immunoglobulins, also known as antibodies, are membrane-bound or secreted glycoproteins produced by B lymphocytes. In the recognition phase of humoral immunity, the membrane-bound immunoglobulins serve as receptors which, upon binding of a specific antigen, trigger the clonal expansion and differentiation of B lymphocytes into immunoglobulins-secreting plasma cells. Secreted immunoglobulins mediate the effector phase of humoral immunity, which results in the elimination of bound antigens. The antigen binding site is formed by the variable domain of one heavy chain, together with that of its associated light chain. Thus, each immunoglobulin has two antigen binding sites with remarkable affinity for a particular antigen. The variable domains are assembled by a process called V-(D)-J rearrangement and can then be subjected to somatic hypermutations which, after exposure to antigen and selection, allow affinity maturation for a particular antigen.
Synonyms: IGLV548; V4-3
Gene: Immunoglobulin variable (V) gene on chromosome 22 (22,352,940 to 22,353,433, forward strand). Ensembl gene ENSG00000211647.
Subcellular location: Secreted; Cell membrane
Gene Ontology:
Biological process: immune response
Cellular component: extracellular region; immunoglobulin complex; plasma membrane
Homologues: Paralogues in human: IGLV5-45 (90% identical), IGLV5-37 (87% identical), IGLV5-52 (78% identical), IGLV11-55 (70% identical), IGLV4-60 (57% identical), IGLV4-69 (56% identical), VPREB1 (51% identical), IGLV2-18 (50% identical), IGLV3-21 (50% identical), IGLV1-40 (50% identical), IGLV2-11 (50% identical), IGLV2-23 (50% identical), and 81 more.